PTN (pleiotrophin)
Description:
Secreted growth factor that mediates its signal through cell-surface proteoglycan and non-proteoglycan receptors. Binds cell-surface proteoglycan receptor via their chondroitin sulfate (CS) groups. Thereby regulates many processes like cell proliferation, cell survival, cell growth, cell differentiation and cell migration in several tissues namely neuron and bone. Also plays a role in synaptic plasticity and learning-related behavior by inhibiting long-term synaptic potentiation (By similarity). Binds PTPRZ1, leading to neutralization of the negative charges of the CS chains of PTPRZ1, inducing PTPRZ1 clustering, thereby causing the dimerization and inactivation of its phosphatase activity leading to increased tyrosine phosphorylation of each of the PTPRZ1 substrates like ALK, CTNNB1 or AFAP1L2 in order to activate the PI3K-AKT pathway. Through PTPRZ1 binding controls oligodendrocyte precursor cell differentiation by enhancing the phosphorylation of AFAP1L2 in order to activate the PI3K-AKT pathway. Forms a complex with PTPRZ1 and integrin alpha-V/beta-3 (ITGAV:ITGB3) that stimulates endothelial cell migration through SRC dephosphorylation and activation that consequently leads to ITGB3 'Tyr-773' phosphorylation. In adult hippocampus promotes dendritic arborization, spine development, and functional integration and connectivity of newborn granule neurons through ALK by activating AKT signaling pathway (By similarity). Binds GPC2 and chondroitin sulfate proteoglycans (CSPGs) at the neuron surface, leading to abrogation of binding between PTPRS and CSPGs and neurite outgrowth promotion (By similarity). Binds SDC3 and mediates bone formation by recruiting and attaching osteoblasts/osteoblast precursors to the sites for new bone deposition (By similarity). Binds ALK and promotes cell survival and cell proliferation through MAPK pathway activation. Inhibits proliferation and enhances differentiation of neural stem cells by inhibiting FGF2-induced fibroblast growth factor receptor signaling pathway (By similarity). Mediates regulatory mechanisms in normal hemostasis and in hematopoietic regeneration and in maintaining the balance of myeloid and lymphoid regeneration (By similarity). In addition may play a role in the female reproductive system, auditory response and the progesterone-induced decidualization pathway (By similarity).
Synonyms: HBBM; HBGF-8; HB-GAM; HBNF; HBNF-1; OSF-1; NEGF1; HBGF8; HARP
Tractability: Antibody: UniProt places it where antibodies can reach, with high confidence; its Gene Ontology location is reachable by antibodies, with high confidence; UniProt predicts a signal peptide or a membrane-spanning region. PROTAC: its protein half-life has been measured; a small molecule that binds it is known.
Target class: Secreted protein
Gene: Protein-coding gene on chromosome 7 (137,227,341 to 137,344,358, reverse strand). Ensembl gene ENSG00000105894.
Subcellular location: Secreted
Subcellular location (Human Protein Atlas): Endoplasmic reticulum; Predicted to be secreted
Pathways (Reactome):
Signal Transduction: MDK and PTN in ALK signaling; Signaling by ALK
Gene Ontology:
Molecular function: carbohydrate binding; chondroitin sulfate binding; growth factor activity; heparin binding; integrin binding; molecular function activator activity; protein binding; protein kinase binding; protein phosphatase inhibitor activity
Biological process: integrin-mediated signaling pathway; ossification involved in bone remodeling; positive regulation of cell population proliferation; positive regulation of oligodendrocyte differentiation; receptor clustering; cell surface receptor protein tyrosine phosphatase signaling pathway; decidualization; dendrite arborization; dendrite regeneration; estrous cycle; learning; leukocyte chemotaxis involved in inflammatory response; memory; negative regulation of long-term synaptic potentiation; negative regulation of neuroblast proliferation; nervous system development; oogenesis; positive regulation of axon regeneration; positive regulation of bone mineralization; positive regulation of dendrite development; positive regulation of hepatocyte proliferation; positive regulation of leukocyte chemotaxis; positive regulation of neuron projection development; positive regulation of ossification; positive regulation of stem cell differentiation; and 9 more
Cellular component: endoplasmic reticulum; extracellular region; protein-containing complex; plasma membrane; Schaffer collateral - CA1 synapse
Genetic constraint (gnomAD): Loss-of-function variants: 11 observed, 18.28 expected, observed/expected ratio (o/e) 0.6, 90% interval 0.38 to 1. The upper end of that interval is the gene's LOEUF score, 1, which puts it in group 4 of 6, group 1 being the genes least tolerant of losing a copy. Missense variants: 144 observed, 174.3 expected, observed/expected ratio (o/e) 0.83, 90% interval 0.72 to 0.95. Synonymous variants: 76 observed, 60.72 expected, observed/expected ratio (o/e) 1.25, 90% interval 1.04 to 1.51.
Homologues: Orthologues: macaque PTN (99% identical), dog PTN (98% identical), mouse Ptn (98% identical), rat Ptn (98% identical), pig PTN (95% identical), guinea pig PTN (95% identical), chimpanzee PTN (90% identical), rabbit PTN (90% identical), tropical clawed frog ptn (65% identical), zebrafish ptn (59% identical). Paralogues in human: MDK (41% identical).
Diseases named in the same sentence as PTN in open-access papers:
PTN is named in the same sentence as 153 diseases in open-access papers, as found by Europe PMC text mining. Sharing a sentence is not in itself a finding about the gene and the disease. The quoted sentences say what the papers report.
glioma (49 papers, 2016 to 2026). A benign or malignant brain and spinal cord tumor that arises from glial cells (astrocytes, oligodendrocytes, ependymal cells). "PTN also contributes to angiogenesis in gliomas and increased expression of PTN is associated with poor survival in glioma patients." (PMID 38012322, 2023). "PTN, being a neurotrophic cytokine, has been studied in the context of neuronal development and has been associated with invasive glioma." (PMID 36828390, 2023). "The decrease in the CREB3L1 mRNA expression was associated with the increase in the PTN mRNA expression in the low- and high-grade gliomas (P<0.05)." (PMID 29531016, 2018). "PTN has been implicated in maintaining the stemness of glioma initiating cells, but its role in early gliomagenesis has not been investigated." (PMID 27806344, 2016). "PTN is up-regulated in glioma, and its expression is associated with poor survival in astrocytomas and glioblastoma." (PMID 27806344, 2016). "In malignant CNS disorders including glioblastoma, PTN secreted by neural precursors as well as tumor-associated macrophages promotes glioma growth and invasion into the subventricular zone, suggesting a role of PTN in cell proliferation and survival of CNS resident cells." (PMID 35046956, 2021). "Here, we show that gain of chromosome 7 in human gliomas is associated with up-regulation of PTN." (PMID 27806344, 2016). "Thus, increased PTN expression in glioma is associated with amplification of chromosome 7." (PMID 27806344, 2016). "In gliomas, both MK and PTN are consistently overexpressed, with expression increasing alongside tumor grade in IDH1 wild-type tumors, correlating with poor patient survival." (PMID 41955968, 2026). "Beyond direct tumor-cell effects, accumulating evidence indicates that MK and PTN shape the glioma microenvironment by promoting macrophage recruitment and polarization, modulating immune signaling, and influencing vascular remodeling." (PMID 41955968, 2026). "In contrast, TUBA1B-low-expressing Glioma cells mainly transmitted signals through the PTN pathway and received signals via the PTN, MK, EGF, and CALCR pathways." (PMID 40094001, 2025). "The three glioma subtypes, along with other cell types, were considered potential targets, highlighting their correlations within the PTN signaling pathway in a hierarchical plot." (PMID 39975552, 2025). "Violin plots highlight cellular interactions, showing the NUSAP+ Glioma subpopulation in the C2 group with elevated activity in the PTN signaling cascade." (PMID 39975552, 2025). "In vivo studies employing shRNA-induced PTN knockdown have revealed a significant decrease in glioma infiltration towards the SVZ." (PMID 40136662, 2025). "PIWIL4 has been shown to promote neuronal differentiation in stem cell models and modulate glioma-related factors such as PTN and NLGN3." (PMID 41228218, 2025). "For TUBA1B-high-expressing Glioma cells, signal output was primarily through the PTN, ANNEXIN, VEGF, PROS, and BMP pathways, while signal input occurred via the PTN, SPP1, and MK pathways." (PMID 40094001, 2025). "In other tumours, it has been reported that neural precursor cells can mediate glioma cell invasion towards the lateral to the subventricular zone (SVZ) by secreting PTN molecules." (PMID 40624675, 2025). "In glioma, the PTN-PTPRZ1 axis promotes malignant growth through paracrine signaling, thus suggesting PTN-PTPRZ1 is a viable target in glioma." (PMID 39518121, 2024). "Further studies targeting NRG3-ERBB4 and PTN-PTPRZ1 ligand-receptor pairs will help to provide a new indicative strategy for the treatment of gliomas." (PMID 38383423, 2024). "Secreted signals in MAN1C1-expressing glioma cells, such as PTN, MIF, ANXA1, MDK, and NAMPT, allowed MAN1C1 to interact with myeloid/microglial cells." (PMID 39333557, 2024).
glioma (continued). "Furthermore, several reports have suggested that PTPRZ-dependent signaling via its ligand pleiotrophin, which is abundantly secreted from tumor-associated macrophages, neural precursor cells, and glioma cells, supports glioma growth and invasion and the maintenance of glioma stem cells." (PMID 37543361, 2023). "GIMs can secret abundant pleiotrophin (PTN) to stimulate glioma stem cells (GSCs) through its receptor PTPRZ1 thus promoting GBM malignant growth through PTN-PTPRZ1 paracrine signaling." (PMID 36036011, 2022). "Conversely, disrupting PTN expression in macrophages reduces the number of SOX2+ glioma cells in GBM bearing mice." (PMID 36555253, 2022). "Studies in murine glioma models have provided evidence that PTN can enhance tumor growth through stimulation of the tumor vasculature." (PMID 31690961, 2020). "Population distribution for the CREB3L1- and PTN-presenting patients was examined in patients with low- and high-grade gliomas, as well as a control group." (PMID 29531016, 2018). "CREB3L1+ cell counts were decreased with increased PTN+ cells in the low-grade and high-grade glioma tissues as compared with the control." (PMID 29531016, 2018). "The CREB3L1 mRNA level in the brain specimens displayed a gradient decrease with an increase in the PTN mRNA level from the control to high-grade glioma tissues." (PMID 29531016, 2018). "PTN also boosts the occurrence of glioma induced by platelet-derived-growth-factor-B via promoting the proliferation of neural precursor cells." (PMID 30427932, 2018). "Concurrently, population proportion for the PTN+ cells progressively increased to 82 and 100% in the cohorts with the low- and high-grade gliomas as compared with the control of 11%." (PMID 29531016, 2018). "Up-regulation of PTM gene expression has been found based on the reports in which the human PTN gene localized on chromosome 7 is often amplified in gliomas." (PMID 29531016, 2018). "In terms of PTN examination, a median value (IQR) for the PTN mRNA expression levels were shown as 0.13 (0.04) in the control, 0.67 (0.58) and 1.12 (0.66) in the low- and high-grade gliomas, respectively." (PMID 29531016, 2018). "The percentage of PTN+ patients was significantly increased in high- and low-grade gliomas (n=17 and 25) as compared with a positive population in the control (n=9), respectively." (PMID 29531016, 2018). "PTN mRNA was detected in high-grade gliomas since the tumors constitutively express and secrete PTN." (PMID 29531016, 2018). "CREB3L1 and PTN mRNA expression was measured in the brain specimens obtained from the control glial cells, low- and high-grade glioma cells." (PMID 29531016, 2018). "Population proportion of the CREB3L1+-presenting patients decreased from the control to the high-grade glioma and the population of the PTN+-presenting patients increased in low- and high-grade gliomas as compared with the control (both P<0.05)." (PMID 29531016, 2018). "The PTN mRNA expressions levels in low- and high-grade gliomas were obviously changed considerably with 5.15- and 8.62-fold increases over the control." (PMID 29531016, 2018). "Based on our data and these reports, it is conceivable that the changes in the CREB3L1 and PTN expression levels were related to the aggressive behaviors (invasion and metastasis) of the glioma cells in disease progression." (PMID 29531016, 2018). "PTN+ cell counts significantly increased in low- and high-grade gliomas as compared with the control." (PMID 29531016, 2018). "Herein, we report that TAMs secrete abundant pleiotrophin (PTN) to stimulate glioma stem cells (GSCs) through its receptor PTPRZ1 thus promoting GBM malignant growth through PTN–PTPRZ1 paracrine signalling." (PMID 28569747, 2017). "We have previously demonstrated that PTN induces vascular abnormalization in GL261 orthotopic glioma and that PTN expression correlates with enlarged vascular lumens and abnormal vessel morphology in human glioblastomas." (PMID 27806344, 2016).
glioma (continued). "PTN mRNA expression was significantly higher in lower-grade glioma (LGG) and glioblastoma samples that showed a gain of chromosome 7 as compared to diploid tumors." (PMID 27806344, 2016). "To elucidate the role of PTN in tumor initiation we employed the RCAS/tv-a model that allows glioma induction by RCAS-virus mediated expression of oncogenes in neural progenitor cells." (PMID 27806344, 2016). "PTN/ALK signaling has previously been shown to be required for maintenance of glioma initiating cells." (PMID 27806344, 2016). "PTN can stimulate glioma cell migration and proliferation, and blocking PTN or its receptors reduces tumor growth." (PMID 27806344, 2016). "This review synthesizes current knowledge on the molecular and cellular functions of MK and PTN in glioma biology, with particular emphasis on their partially overlapping yet distinct receptor and signaling networks that govern tumor cell survival, metabolic adaptation, and invasion." (PMID 41955968, 2026). "For glioma efferent signaling, mode 1 was characterized by pathways such as PTN and NCAM." (PMID 39975552, 2025). "We identified all eight cell types within glioma tissues as origins of the PTN signaling cascade." (PMID 39975552, 2025). "PTN signaling helps maintain glioblastoma stem cells and facilitates glioma cell invasion." (PMID 36828390, 2023). "And Pleiotrophin (PTN) is considered as a potential target for glioma treatment." (PMID 37170286, 2023). "GBM cells from all four clusters expressed up to 10 different MDK/PTN receptor genes, suggesting that these GBM cells can respond to MDK and PTN cytokines produced by the glioma microenvironment and/or produced auto-/ paracrine by GBM cells, as demonstrated for GBM-34, -49, -109, and -228." (PMID 34502484, 2021). "The receptors for EGF (EGFR) and PTN (PTPRZ1) have important roles in the genesis of gliomas." (PMID 33925547, 2021). "Genetic knockdown of PTN, on the other hand, strongly reduces glioma invasion." (PMID 32178267, 2020). "In particular, high levels of pleiotrophin and its respective receptor (protein tyrosine phosphatase receptor type z, PTPRz) are expressed in a subset of human glioblastomas; in general, pleiotrophin abundance is higher in human high-grade gliomas and is correlated with poor survival of patients." (PMID 33036204, 2020). "NPCs may be involved in the tropism of GSCs, because NPCs in the subventricular zone have been shown to secrete the neurite outgrowth-promoting factor pleiotrophin that is one of key chemoattractants for glioma invasion." (PMID 31060588, 2019). "CREB3L1 and PTN expression levels serve as biomarkers with utility in grading gliomas." (PMID 29531016, 2018). "CREB3L1 and PTN expressions have been involved in human gliomas." (PMID 29531016, 2018). "Given that the PTN protein was overexpressed in the brain glioma patients, its blockade could be a potential target for a treatment strategy of the gliomas as the tumors still remain a therapeutic challenge." (PMID 29531016, 2018). "Similarly, pharmacological CDK5 inhibition by roscovitine or genetic CDK5 down-regulation, by means of siRNA, abolished PTN-induced migration of human glioma U87MG cells." (PMID 29651006, 2018). "Knockdown of pleiotrophin in SVZ reduced glioma invasion of the SVZ in the murine brain." (PMID 30279357, 2018). "In a latest study, the levels of PTN mRNA and protein was significantly correlated with high histological grade, low Karnofsky Performance Status score, short time to recurrence and poor overall survival in human glioma." (PMID 30427932, 2018). "Furthermore, changes in the CREB3L1 and PTN expression levels in the tumor cells offer the potential to assess prognosis of the glioma patients." (PMID 29531016, 2018).